INS (insulin)
Diseases named in the same sentence as INS in open-access papers (continued):
Sharing a sentence is not in itself a finding about the gene and the disease.
Insulin resistance (continued). "T2DM is characterized by insulin resistance, decreased glucose utilization, increased glucose accumulation, and impaired insulin secretion." (PMID 35747025, 2022). "Significant differences in HOMA-IR [homeostasis model assessment of insulin resistance index, fasting plasma insulin (mU/mL) × fasting glucose (mmol/L)/22.5] and plasma irisin levels between the two groups were found." (PMID 36741990, 2022). "Type 2 diabetes mellitus (T2DM) has a significant social and economic burden which is identified by high blood glucose levels (hyperglycemia) due to insulin resistance, insulin secretion, or both." (PMID 35870947, 2022). "Due to the differences in aging signatures in various tissues, and these differences in insulin resistance development due to aging, it would be difficult to fully link insulin resistance between all tissues at any given time." (PMID 35884888, 2022). "The functional consequences of this include an increase in NFkB and Activator Protein 1 (AP-1) signaling, leading to more inflammatory signals (IL-1β, TNF-α, and IL-6) that alter insulin sensitivity and later culminate in aggravated insulin resistance." (PMID 35682832, 2022). "It is well known that both insulin resistance and insulin secretion defects are two core mechanisms during the development of DM." (PMID 35185617, 2022). "An imbalance in the gut microbiota can lead to lower insulin levels, insulin resistance, and a subsequent rise in blood glucose levels." (PMID 35418976, 2022). "Taking vaspin in obese mice improves glucose tolerance, insulin sensitivity and modifies the expression of genes responsible for insulin resistance." (PMID 36291064, 2022). "T2DM is a complex metabolic disorder characterized by hyperglycemia arising from the combination of an impaired insulin secretion, increased hepatic glucose production, and a decreased insulin-mediated glucose uptake (insulin resistance)." (PMID 35163825, 2022). "In type 2 diabetes, the development of insulin resistance ultimately promotes a reduction in insulin production and the failure of pancreatic beta cells." (PMID 35930075, 2022). "The glycation of proteins with short half-lives, such as insulin, can lead to the formation of advanced glycation end products (AGEs), resulting in insulin resistance." (PMID 36295897, 2022). "Hippocampal insulin resistance is characterized by the insensitivity of hippocampal IRs and decreased phosphorylation of insulin downstream signaling molecules." (PMID 36430894, 2022). "In animal models, UDCA decreased fasting glucose, insulin, and hepatic insulin resistance, concluding that UDCA is effective in treating hepatic steatosis accompanied by T2DM." (PMID 36558967, 2022). "In skeletal muscle and liver, autophagy stimulates INS pathway activity, while in the pancreas, autophagy destroys pancreatic β-cells to induce insulin resistance, thus suggesting that autophagy can regulate the role of INS." (PMID 36589825, 2022). "Obesity (represented by both high WHR and BMI) is usually accompanied by insulin resistance and insensitivity due to the effect of visceral fat on insulin secretion and clearance." (PMID 35621355, 2022). "Weight gain was positively correlated with insulin increase (r = 0.48, p < 0.001) and with the insulin resistance indexes, HOMA (r = 0.48, p < 0.001) and triglycerides/HDL (r = 0.51, p < 0.001)." (PMID 35971658, 2022). "Saturated fatty acid was associated with insulin resistance, while n-3 PUFA, n-6 PUFA, MUFA, especially n-3/n-6 ratio and triene/tetraene ratio were positively associated with insulin sensitivity." (PMID 35846301, 2022). "AAP remarkably suppressed fasting glucose and fasting insulin levels and improved the insulin resistance state in mice." (PMID 35407029, 2022). "For the past few years, AD has also been considered as “type 3 diabetes” because of insulin resistance (IR) and dysregulation of insulin signaling in the brain." (PMID 36465634, 2022).
Insulin resistance (continued). "Male NG2-ChR2 mice fed HFD for 16 weeks presented obesity, hyperglycemia, glucose intolerance, insulin resistance, defective glucose-stimulated insulin release (GSIS), and changes in islet gene expression such as Ins1, Ins2 and Gck." (PMID 35813647, 2022). "PPARδ is engaged in glucose and lipid metabolism in the liver and exerts insulin-sensitizing effects, thereby improving hepatic insulin resistance." (PMID 36051387, 2022). "Alteration in insulin sensitivity, called insulin resistance, is a specific and early characteristic of T2D that results in impaired glucose removal." (PMID 35547584, 2022). "Our study showed that in NAFLD mice with VEGFB knockout, blood glucose level increased markedly, glucose tolerance was impaired, insulin resistance was distinct, and insulin sensitivity descended." (PMID 35907871, 2022). "High blood levels of insulin due to insulin resistance often lead to steatosis in the liver because of SREBP-1 activation, and the suppression of SREBP-1 means protection against the development of a fatty liver." (PMID 36362221, 2022). "Antioxidants are crucial to scavenge ROS in metabolic disorders since excess ROS are involved in insulin signal dysregulation, insulin resistance, overfeeding, saturated fatty acids, and chronic inflammation." (PMID 36185651, 2022). "Fasting insulin levels, insulin resistance index, follicle-stimulating hormone, luteinizing hormone, and estrogen are the family members of heterodimeric glycoprotein hormones, all of which participate in the development of EC." (PMID 35752750, 2022). "Increased concentrations of plasma insulin in the basal state in humans with insulin resistance suppresses skeletal muscle protein breakdown." (PMID 35350688, 2022). "Patients with acromegaloid have increased growth hormone and insulin resistance, which makes them insulin-dependent." (PMID 36141396, 2022). "A correlation was made between the number of SCs and BMI, serum insulin, and the insulin resistance (IR) index HOMA." (PMID 35247131, 2022). "In this study, we investigated the mechanism of naringin that affects the metabolic processes and enhanced insulin sensitivity of the skeletal muscles in the HFD-induce insulin resistance obese rat model." (PMID 36235772, 2022). "During IPITTs, db/db mice showed greater insulin resistance, manifested by a reduced hypoglycemic effect of insulin and increased AUC compared to WT mice (P < 0.05)." (PMID 35585884, 2022). "According to previous studies, the administration of walnut extract for 6 weeks in streptozotocin (STZ)-induced diabetic CD rats reduced blood glucose levels and increased insulin sensitivity by ameliorating insulin resistance." (PMID 36014555, 2022). "This includes elevated fasting plasma glucose, altered glucose and insulin tolerance tests indicative of insulin resistance and increased circulating levels of insulin and leptin." (PMID 35204736, 2022). "Old SAMP8 male mice also showed insulin resistance together with a decrease in insulin production by the endocrine pancreas and a reduced expression of differentiation parameters." (PMID 35887196, 2022). "IP6K1 is relevant in human metabolic diseases as its levels positively correlate with HOMA-IR (Homeostatic Model Assessment for Insulin Resistance) in prediabetic subjects and negatively corelate to insulin sensitivity." (PMID 35216174, 2022). "Fasting glucose and insulin concentrations and derived indices of insulin resistance (HOMA-IR), β-cell function (HOMA-%B), and insulin sensitivity were determined at baseline and 28 weeks’ gestation." (PMID 36137169, 2022). "On the other hand, DNJ improved insulin signaling and insulin resistance through the expression of these proteins in the after treatment group." (PMID 36364802, 2022). "If the insulin values are elevated, and depending on the amount of glucose values, the diagnosis of insulin resistance, hyperinsulinemia, or even type 2 diabetes is made." (PMID 35628058, 2022).
Insulin resistance (continued). "In individuals with obesity, impaired insulin action leads to increased lipolysis in adipocytes, resulting in elevated plasma free fatty acid (FFA) levels that promote peripheral insulin resistance, a hallmark of T2D." (PMID 35351896, 2022). "As obesity causes insulin resistance and cardiometabolic disease, we examined the association of serum EMC10 with insulin sensitivity and other cardiometabolic traits." (PMID 36443308, 2022). "In particular, we observed an improvement in insulin sensitivity, as measured by HOMA2-%S, of fasting glucose, insulin, and insulin resistance index." (PMID 35889926, 2022). "Metformin can reduce the level of insulin resistance in patients, improve insulin sensitivity, reduce hepatic glucose production, and promote the normalization of glucose metabolism." (PMID 35368950, 2022). "This insulin resistance results from decreased insulin sensitivity in tissues such as adipose, skeletal muscle, and liver tissues." (PMID 35320949, 2022). "Recently we have reported the differential role of Akt isoforms in regulating neuronal insulin signaling and insulin resistance." (PMID 36376971, 2022). "Total cholesterol, LDL, triglycerides, insulin, and insulin resistance were significantly higher in participants with low serum vitamin B12 levels compared with those with serum levels higher than the median." (PMID 36553749, 2022). "The relatively enhanced activation of ACE2/Ang1-7/MasR reverses and prevents local and systemic dysfunction, thereby improving lipid distribution and insulin resistance by regulating insulin action and reducing inflammation." (PMID 36253996, 2022). "Shifting to the production of pro-inflammatory cytokines leads to low-grade systemic inflammation leading to impaired insulin signaling, beta-cell dysfunction, and subsequent insulin resistance." (PMID 36188222, 2022). "Type 2 Diabetes (T2D) is a chronic disease characterized by abnormally high blood glucose levels due to insulin resistance and reduced pancreatic insulin production." (PMID 35178244, 2022). "IRS-1 causes insulin resistance, while IRS-2 is needed for hepatic insulin activity, and its increase is related to prediabetes." (PMID 36290594, 2022). "The development of T2DM is characterized by a decrease in insulin sensitivity, also called insulin resistance, resulting in hyperglycemia." (PMID 36139776, 2022). "As the focus of these studies is on insulin sensitizing agents, they should include a measure of insulin resistance, which at the most basic form would require fasting samples of glucose and insulin." (PMID 36347837, 2022). "Insulin resistance is defined as a decreased response to a given amount of insulin and is a central contributing factor to the pathogenesis of type 2 diabetes mellitus (T2DM)." (PMID 35457158, 2022). "Vitamin D can also modulate insulin sensitivity by activating peroxisome proliferator-activated receptors-δ, which reduces free fatty acid-induced insulin resistance." (PMID 36313112, 2022). "It is well known that insulin resistance in T2DM results in impaired insulin-stimulated intramuscular glycogen synthesis." (PMID 35897066, 2022). "Obesity can lead to insulin resistance (IR) with compensatory insulin secretion to maintain glucose homeostasis." (PMID 35669687, 2022). "Folic acid and vitamin B12 supplementation improve T2D by reducing OS, reverting DNA damage, improving glycemic control, and reducing serum insulin, insulin resistance, and homocysteinemia." (PMID 36632095, 2022). "The 16-week intervention of aqua exercise decreased the levels of insulin, glucose, homeostasis model assessment of insulin resistance, and thromboxane A2, but increased the levels of the quantitative insulin sensitivity check index and prostaglandin I2." (PMID 36295873, 2022). "The mass and proliferation of pancreatic β-cells in the presence of obesity and aging conditions are initially elevated by the increased demand for insulin due to the development of insulin resistance." (PMID 35563231, 2022).
Insulin resistance (continued). "Obesity can stimulate the formation of lipid metabolites, cytokines, and hormones, which involves changes in the insulin signaling pathway and accelerates progression of insulin resistance." (PMID 36246637, 2022). "DI is calculated by insulin secretion/insulin resistance (ΔI/ΔG ÷ IR), with several formulas being proposed depending on available measurements." (PMID 35163144, 2022). "The adipose tissue releases adipokines, hormones, and free fatty acid that modulate glucose and lipid metabolism, insulin sensitivity, and inflammation; thus, excessive secretion of these molecules can contribute to insulin resistance and hepatic steatosis." (PMID 35013484, 2022). "There was a positive correlation between exposure and improvement of HbA1c, which was accompanied by reduced body weight and insulin resistance, ameliorated insulin secretion and lower systolic blood pressure." (PMID 35545657, 2022). "For example, given that insulin resistance is the main reason for type 2 diabetes, miRNAs can modulate proteins engaged in insulin signaling, thus affecting insulin resistance and glucose homeostasis." (PMID 34984663, 2022). "They showed that the exposure of Fao rat hepatoma cells to titanium dioxide nanoparticles altered insulin response and induced insulin resistance by interfering with insulin-signaling and by indirect inflammatory activation of macrophages." (PMID 35548681, 2022). "The dysfunction of signal transmission leads to the translocation of glucose transporter type 4 (GLUT4) and the disturbance of insulin signaling pathway, which further triggers insulin resistance and more insulin secretion." (PMID 36338055, 2022). "We investigated the effects of IRW on body composition, glucose homeostasis and insulin sensitivity in a high-fat diet (HFD) induced insulin resistant (IR) model." (PMID 35740257, 2022). "Gestational diabetes mellitus (GDM), which affects 2-22 percent of all pregnancies, has a genetic background that is similar toT2D, including decreased insulin production and insulin resistance." (PMID 36589630, 2022). "FoxOs are inactivated by insulin, and it is widely believed that they are constitutively active in settings of insulin resistance." (PMID 35104242, 2022). "Overall, the physiological role of FGF21 is to act on white adipose tissue lipolysis, increase insulin-dependent glucose uptake, and revert insulin resistance." (PMID 36140410, 2022). "Luteolin decreases insulin resistance and improves insulin production and action through activation of the PPARγ pathway." (PMID 35458669, 2022). "By activating the nuclear receptor for PPARγ, which is associated with insulin resistance, adiponectin has become a marker of both insulin sensitivity and insulin resistance." (PMID 35628118, 2022). "The classical view is that placental hormones, prolactin, progesterone, and glucocorticoid antagonize the increased insulin level and insulin resistance during pregnancy is an important factor in the pathogenesis of GDM." (PMID 36263320, 2022). "Markers of glucose homeostasis, namely fasting plasma glucose and insulin, and homeostatic model assessment of insulin resistance (HOMA-IR) decreased significantly among the pemafibrate groups compared to placebo." (PMID 35457120, 2022). "In contrast to the previous research markers of current (fasting insulin, glucose levels, and marker of insulin resistance) and long-term (glycated hemoglobin) glucose levels were included in the study." (PMID 35710822, 2022). "Some authors suggest that gallic acid from roselle is responsible for increased insulin secretion through the regeneration of β islets in the pancreas, which in turn improves insulin sensitivity and reduces insulin resistance." (PMID 35885378, 2022). "Stimulation of AMPK activity improves insulin sensitivity, and sustained decreases in AMPK activity in obesity are associated with insulin resistance." (PMID 35789435, 2022).
Insulin resistance (continued). "Insulin resistance results in increased β-cell insulin production, which leads to weight gain, perpetuating a cycle of insulin resistance." (PMID 36499769, 2022). "It has been reported that myo-inositol is a modulator of insulin regulation and glucose homeostasis in animal models of insulin resistance." (PMID 36077553, 2022). "IP6K1 impairs insulin signaling by inhibiting the insulin effector protein kinase Akt, promoting high-fat diet-induced insulin resistance." (PMID 35216174, 2022). "GLP-1RA has a significant effect on weight loss, can increase insulin secretion and slow the progress of DKD; thus, it is more suitable for the SIRD population with obesity, high insulin resistance and high incidence of DKD." (PMID 36457559, 2022). "GDM is defined by glucose intolerance with onset during pregnancy and appears when insulin resistance exceeds the capacity of pancreas to secrete insulin." (PMID 36080270, 2022). "A healthy pregnancy is characterized by transient insulin resistance and hyperlipidemia, among other changes, resulting in increased insulin secretion to secure normal glucose tolerance." (PMID 35203692, 2022). "It is well established that insulin resistance is related to blood pressure and that subjects with hypertension demonstrate a decreased insulin sensitivity even at the early stage of the disease." (PMID 35439985, 2022). "Compared with the TN group, the levels of insulin, insulin resistance index, TG, and TC increased, and the level of NEFA decreased, in the HT group (p < 0.05)." (PMID 35405834, 2022). "Recently, enzymes of InsPs metabolism have been related to insulin signaling, insulin resistance, and type 2 diabetes." (PMID 36364861, 2022). "Studies on insulin resistance found that the culprit behind this key event in type 2 diabetes development is damage in the insulin signaling pathway, more precisely in the phosphorylation of IRS on serine and threonine residues." (PMID 36012159, 2022). "The liver insulin IRS1/PI3K/AKT signaling pathway is of great significance in improving hepatic insulin resistance." (PMID 36676939, 2022). "In one instance, protection from age-related insulin resistance is achieved through a primary decrease in insulin synthesis, which also limits HFD-induced beta-cell mass expansion and decreases fasting insulinemia." (PMID 34823065, 2022). "According to De Koster and Opsomer, based on data from an IVGTT, insulin resistance identified by lesser glucose and insulin CR, greater AUC, and higher the T1/2 and Tbase." (PMID 36153497, 2022). "The levels of insulin and insulin resistance are influenced by the accumulation of WAT, and the levels of insulin can affect the secretion of insulin-like growth factor-1 (IGF-1)." (PMID 35215391, 2022). "There are various indices for insulin resistance, and a more in-depth analysis would have been possible if we had measured postprandial insulin and glucose." (PMID 36086748, 2022). "Insulin levels, homeostatic model assessment of insulin resistance (HOMA-IR), fasting plasma glucose (FPG), and glycosylated hemoglobin A1C (HbA1c) were defined as the primary outcome markers, and lipid profiles were considered the secondary outcome markers." (PMID 36432623, 2022). "With the univariable analysis, the BMI SDS, triglycerides (TG), insulin, homeostatic model assessment for insulin resistance (HOMA-IR), APRI, uric acid and metabolic syndrome were positive predictors of NAFLD, with female sex being negative predictor." (PMID 35208229, 2022). "The genetic variants related to T2DM in Caucasians are mainly related to insulin resistance, but those in Asians, including Chinese, Japanese, and Koreans, are involved in insulin secretion (GLP1R, PAX4, HNF4A, SLC30A8, HHEX, CDKAL1, CDKN2A/B, and GCKR)." (PMID 35956399, 2022). "In this regard, and in the presence of resistance to the action of insulin in muscle, the expectation is that humans with obesity/insulin resistance have increased rate of muscle protein breakdown." (PMID 35350688, 2022).